FLNA (filamin A)
Diseases named in the same sentence as FLNA in open-access papers (continued):
Sharing a sentence is not in itself a finding about the gene and the disease.
cancer (114 papers, 2010 to 2026). A tumor composed of atypical neoplastic, often pleomorphic cells that invade other tissues. "These analyses identified ITGA2B and FLNA consistently upregulated and functionally relevant in platelet signaling and cancer-associated thrombosis." (PMID 41226816, 2025). "Stimulated by androgens, the AR/FlnA complex in cancer-associated fibroblasts (CAFs) recruits integrin β1 and activates Rac1 and FAK, thereby facilitating the migration of PCa cells." (PMID 39055653, 2024). "In a related process, arsenic induced carcinogenesis caused S2152A mutagenesis, nullified filamin-A S2152 phosphorylation by Akt and ameliorated cancer cell migration in the human bronchial epithelial cell line, BEAS-2B." (PMID 38958472, 2024). "Needless to say, as the fragmentation of filamin A by proteolytic cleavage is irreversible, it is associated with many diseases including cancer and disorders of the cardiovascular and nervous systems." (PMID 38958472, 2024). "The FLNA protein participates in the regulation of the calcium-sensing receptor and has been associated with increased aggressiveness in a wide range of cancers." (PMID 36900197, 2023). "An androgen receptor-derived stapled peptide, which disrupts the androgen receptor/filamin A complex assembly, abolishes the androgen-dependent migration and invasiveness of cancer associated fibroblasts." (PMID 33500395, 2021). "Androgen enhances both these effects through androgen receptor/filamin A complex assembly in cancer-associated fibroblasts." (PMID 33500395, 2021). "FLNa is a well known cytoskeletal-associated protein binding a variety of partners and playing different roles in cancer according to its subcellular localization." (PMID 27713116, 2016). "Although a large volume of studies associate filamin-A with cancer metastasis, the specific roles of filamin-A during metastatic invasion remain elusive." (PMID 23388158, 2013). "Mutations and aberrant expression of filamin-A have been reported in human genetic diseases and several types of cancer." (PMID 23388158, 2013). "Initially, FLNa was identified as a cancer-promoting protein implicated in invasion and metastasis." (PMID 38666944, 2024). "This suggests that FLNA gene expression in the immune cell might be linked to the survival of cancer cells." (PMID 34290294, 2021). "As discussed in early sections, various reports have implicated that the levels of filamin-A expression in the cancer cells may be correlated with the cancer metastatic potential and sensitivities to therapeutic DNA damage agents." (PMID 23388158, 2013). "Notably, FLNA was associated with EMT activation in 50% of cancers." (PMID 38584831, 2024). "Interestingly, it has been shown that FLNA down-regulation promotes matrix metalloproteinase secretion, a mechanism that may contribute to the association of FLNA down-regulation and cancer." (PMID 25481874, 2015). "It stands to reason that filamin-A may be required for the cancer cells to remain attached to the original site, and that mis-regulation or loss of filamin-A may increase the risk of initiation of cancer metastasis." (PMID 23388158, 2013). "Different studies have shown that an increased expression of FLNA enhances the epithelial-mesenchymal transition (EMT) in cancer cells." (PMID 40244610, 2025). "CNa 29, a calpain 2‐specific inhibitor, reduced cancer cell proliferation, decreased filamin A cleavage, downregulated TWIST1 expression, and significantly retarded metastasis." (PMID 40151834, 2025). "Taken together, our integrative strategy revealed ITGA2B, FLNA, GRB2, FCGR2A, and APP as high-confidence, FDA-targetable candidates that intersect cancer-associated platelet education with pro-metastatic platelet signaling." (PMID 41226816, 2025). "Specifically, FLNA promotes cancer progression through its interactions with signaling molecules, often leading to adverse outcomes." (PMID 38739940, 2024).
cancer (continued). "Novel discoveries of FLNA functions in cancer development are still underway, but already FLNA is considered as an important player in cancer development and the progression to metastasis." (PMID 39195282, 2024). "Intriguingly, the role of FLNA in cancer development depends significantly on its cellular localization." (PMID 38739940, 2024). "It suggests that the expression level, form, and localization of FLNa are all critical factors in cancer development and metastasis." (PMID 38666944, 2024). "By being present in the cytoplasm and interacting with oncogenic cell signaling molecules, FLNA can promote cancer cell growth and metastasis as well as when present in the nucleus as a part of the transcriptional complex." (PMID 39195282, 2024). "FLNA and FLNB were the most commonly mutated genes related to disulfidptosis in cancer, as revealed by the SNV analysis." (PMID 38584831, 2024). "FLNA is considered to have an important function in cancer development and the progression to metastasis." (PMID 39195282, 2024). "Conversely, when FLNA is situated in the nucleus, it inhibits cancer cell development and migration by either binding with transcription factors or diminishing activity in DNA promoter regions." (PMID 38739940, 2024). "Four cancer driver genes, namely KMT2D, LRP1B, TRRAP, and FLNA, were identified in the 20 most frequently mutated gene sets." (PMID 37373553, 2023). "Pan-cancer driver genes with high alteration rates include FLNA (Filamin A, 41.86%), MUC4 (Mucin 4, 41.86%), and FAT3 (FAT Atypical Cadherin 3, 39.53%)." (PMID 36653483, 2023). "The second subnetwork containing 13 nodes and 12 edges showed the interaction between PRDX2 and TAGLN2 as well as a mild increase in multiple components of the peroxisome (SOD1, CAT, PRDX5, PRDX1) and proteoglycans in cancer (FLNA, STAT3)." (PMID 38322285, 2023). "Previous studies have shown that PrPC interacts with Filamin A (FLNA) to promote cancer progression." (PMID 37894349, 2023). "Particularly, filamin A (FLNA), a cytoskeleton regulator, has been reported as taking on opposite roles depending on the cancer type." (PMID 35008958, 2022). "Although EYS has not previously been investigated in the context of prognosis, the adverse prognostic impact of APC, NOTCH1, ARID1A, and filamin A has been reported in other cancer types." (PMID 33801954, 2021). "When examining the role of mTORC2 in cancer cell migration, the protein complex was found to phosphorylate filamin A, an actin cross-linking protein to maintain focal adhesion dynamics and cell migration." (PMID 35096817, 2021). "It has been further reported that upon overexpression, filamin A attenuates autophagy and suppresses the invasive ability in cancer cells." (PMID 33718218, 2021). "The role of Filamin A has been well studied in cancer progression and other microbial pathogenesis; however, in Leishmania infection biology, its role remains to be investigated." (PMID 34578226, 2021). "The contradictory results from these studies show that the role of FLNa in cancer metastasis and invasion remains elusive." (PMID 34213679, 2021). "A dual role of filamin A in cancer has been suggested to be a consequence of its localization in the cell." (PMID 34771736, 2021). "FLNA plays an important role in cancer development and metastasis by remodeling the actin cytoskeleton." (PMID 33171868, 2020). "Meanwhile, PC1 negatively associated genes included FLNA, ARF5, and SLC25A6, suggesting its connection to cancer development." (PMID 32231683, 2020). "In turn, migration and invasion of cancer cells are based on the formation of actin-rich protrusions (Arp2/3 complex, filamin A, fascin, α-actinin, and cofilin)." (PMID 33036298, 2020). "Data derived from The Cancer Genome Atlas (TCGA) showed that the expression of seven of these genes including EGR1 (early growth response protein 1) and FLNA (filamin A) significantly correlated with the therapy outcome in cisplatin-treated cancer patients." (PMID 32102425, 2020).
cancer (continued). "The role of FLNA in cancer development is controversial and although its overexpression has been observed in several tumors, in some cases opposite roles have been described." (PMID 32545553, 2020). "Filamin A was also found to promote cancer growth and to play an important role in repair of DNA damage." (PMID 32102425, 2020). "FLNA interacts with many proteins related to cancer metastasis and has a role in cancer progression." (PMID 32545553, 2020). "It is believed that signaling factors that interact with FLNA, as well as the subcellular localization, determine the role of FLNA in cancer." (PMID 33266100, 2020). "In orthotopic mouse models, down-regulation of FLNA stimulates cancer cell migration, invasion, and metastasis." (PMID 33171868, 2020). "This latter interacts with filamin A (FLNA) and integrin β1 to disrupt the cytoskeletal organization and promote cancer cell invasiveness and migration." (PMID 31618844, 2019). "Multiple studies have shown that FLNA exhibited opposing roles in cancer progression depending on its location." (PMID 31632499, 2019). "Because of FLNA is considered as an important oncogene in multiple types of cancer owing to its role in cancer cell proliferation, apoptosis and migration." (PMID 31384171, 2019). "Specific missense mutation matches have been found to six proteins from the COSMIC Cancer Gene Census database (FLNA, RPL22, SDHA, NFATC2, NPM1, and CLTCL1)." (PMID 31316139, 2019). "FLNA’s importance in cellular adhesion and migration makes it a critical player in cancer invasion and metastasis." (PMID 29615978, 2018). "Filamin A has also been suggested to suppress cancer cell invasion and migration by regulating focal adhesion." (PMID 29568375, 2018). "FLNA promotes cancer cell migration and invasion, and regulates actin remodeling by activating Rho GTPase." (PMID 28031525, 2017). "In this report we focused on characterization of the potential biomarkers in PrCa cell lines, but it must be noted that FLNA has been described to be dysregulated in a variety of cancers, including ovarian, breast and pancreatic." (PMID 28344825, 2017). "Different studies clearly support a role of a widely-expressed cytoskeleton protein, Filamin-A (FLNA), in cancer progression and metastasis." (PMID 29100390, 2017). "We also showed that FLNA expression increased progressively with malignant grade, as reported in several studies, in which FLNA expression is correlated with cancer aggressiveness." (PMID 29100390, 2017). "Caveolin-1 and filamin A were included in the “Focal Adhesion” and “Proteoglycans in Cancer” pathways." (PMID 28697756, 2017). "Cytoskeleton protein FLNA appears as a crucial element in PNTs cells as demonstrated in various types of cancers, in which FLNA expression is correlated with the cancer metastatic potential." (PMID 29100390, 2017). "The function of FLNA in carcinogenesis and/or in cancer cell migration and invasion is not fully understood." (PMID 25481874, 2015). "On the contrary, under-expression of filamin-A was also observed in some types of cancers, including human bladder cancer and colon adenocarcinoma." (PMID 23388158, 2013). "It is conceivable that the level of filamin-A in cancer tissue can be developed as an alternative marker for outcome prediction and individualized therapy." (PMID 23388158, 2013). "Considering the metastatic role of filamin-A in cancer cell mobility and re-attachment to secondary sites, it is also conceivable to predict that inhibition of filamin-A would also reduce distant cancer metastasis." (PMID 23388158, 2013). "The correlation of filamin-A expression patterns in different stages of cancer tissues and cancer outcomes has been reported." (PMID 23388158, 2013). "It is also possible that cancer cells with appropriate filamin-A levels would likely have an advantage during metastasis." (PMID 23388158, 2013).
cancer (continued). "When compared with normal tissues, increased expression of filamin-A was observed in various types of cancers." (PMID 23388158, 2013). "Extensive studies are required to fully develop filamin-A as a valid cancer marker and therapeutic target." (PMID 23388158, 2013). "In this review, we discuss the implications of filamin-A in cancer progression, including metastasis and DNA damage response." (PMID 23388158, 2013). "Actually, Filamin A plays a dual role in cancer development." (PMID 39215616, 2024). "Human cancers express altered levels of actin-binding cytoskeletal filamin A (FLNA) protein." (PMID 39195282, 2024). "Both cytoplasmic and nuclear FLNA are involved in cancer-related phenotypes depending upon the type and stage of cancer, where cytoplasmic FLNA is particularly involved in cancer cell migration and proliferation, while nuclear FLNA is involved in cancer cell signaling and transcription." (PMID 39195282, 2024). "The wider context of filamin A ubiquitination in NK-cells in treatment of malignant tumours is currently unexplored, and further investigations may yield promising results, deepened further by current excitement surrounding immunotherapy in treating cancer." (PMID 38958472, 2024). "Additionally, the long non-coding RNA LINC01002 demonstrates potential anti-cancer efficacy in PCa by targeting the miR-650/FlnA pathway." (PMID 39055653, 2024). "Since one of the main mechanisms that control FLNA functions and proteolysis is phosphorylation on Ser2152, further studies evaluating FLNA phosphorylation levels in ACCs are needed to further understand the contribute of FLNA to the reduction in cancer progression." (PMID 38068896, 2023). "Furthermore, migration and invasion of cancer cells are based on the formation of actin-rich protrusions (Arp2/3 complex, filamin A, fascin, α-actinin, and cofilin)." (PMID 36983741, 2023). "In summary, this study demonstrates that FLNA may play as a positive regulator in cancer proliferation and recurrence." (PMID 35359350, 2022). "FLNA’s function in the cytoplasm as a scaffolding protein and its vital importance in cell adhesion and migration can transform it into an extremely potent cancer-promoting protein." (PMID 35957887, 2022). "Therefore, the controversial role of FLNA in human malignant tumours has been reported in several studies." (PMID 36105798, 2022). "The role of FLNA in cancers has been studied in multiple types of tumors." (PMID 37435454, 2022). "Previous studies identified the FLNA as determinant in cancer progression and metastasis through affecting cancer cell growth and migration 25, 26, but the role of FLNA in NPC is still unknown." (PMID 34093822, 2021). "FLNa expression or suppression may facilitate or inhibit cancer invasion depending on the cell type, FLNa expression levels, and FLNa’s interactions with other proteins." (PMID 34213679, 2021). "Another mechanism of force sensing in cancer involves filamin A. This actin and actin-integrins crosslinker is down-regulated in human bladder cancer, reducing autophagy in these cancer cells, as indicated by the decrease in the levels of LC3-II and decrease in LC3-I." (PMID 33718218, 2021). "Previous studies showed that FLNa expression or suppression may facilitate or inhibit cancer invasion depending on the cell type, FLNa expression levels, and FLNa interactions with other proteins." (PMID 34213679, 2021). "Although extensively studied, the role of filamin A in cancer remains still controversial." (PMID 34771736, 2021). "It seems that filamin A plays a highly complex and dual role in cancer." (PMID 34771736, 2021). "The availability of a specific inhibitor of the AR/FlnA complex acting downstream of hormone binding could provide a second line option to repress the metastatic potential of hormone refractory cancers bearing constitutively active AR." (PMID 35011576, 2021).
cancer (continued). "Additionally, the level of FlnA correlates with the clinical stage of cancer, lymph node metastasis, and poor prognosis." (PMID 33036298, 2020). "In turn, cytoplasmic FlnA acts as a promoter in cancer invasion and metastasis." (PMID 33036298, 2020). "Due to FLNA’s involvement in cytoskeletal reorganization, cell shape modeling, cell matrix interaction and migration, it is obvious that impairment of FLNA functionality may be relevant for cancer development and progression to metastasis." (PMID 33266100, 2020). "Therefore, the role of FLNA as cancer promoting or suppressing effector requires further clarifications." (PMID 33194682, 2020). "FLNA has been reported as oncogene in some cancers but as tumor suppressor in others." (PMID 33194682, 2020). "The inhibition of cytoskeletal components via miR-200c, like filamin A as shown here, support the role of miR-200c in maintaining the epithelial state and inhibiting the onset of metastasis as possibly important in a wider variety of cancer cells." (PMID 31747409, 2019). "Initially, disclosed as a cancer protein, filamin A played a dual role in cancer." (PMID 29862660, 2018). "Furthermore, our results are in line with the fact that FLNA is overexpressed in multiple types of cancer." (PMID 29615978, 2018). "Since Rap1 is also involved in regulating cell adhesion and proliferation in PNT cells, we speculated that down-regulation of Rap1 expression by FLNA modulates these cellular activities, essential for cancer progression and metastasis development." (PMID 29100390, 2017). "Several studies identified the cytoskeleton protein Filamin A (FLNA) as determinant in cancer progression and metastasis, but the role of FLNA in PNT aggressiveness and progression is still unknown." (PMID 29100390, 2017). "Activation of p38 upregulates FLNA, which promotes cancer cell proliferation." (PMID 26824501, 2016). "Interestingly, one of the filamin members, FLNA, is reported to suppress cancer cell migration and invasion and modulate focal adhesion." (PMID 25577646, 2015). "Accordingly, the findings in this report may be potentially translated into new therapeutic strategies by targeting Akt kinase and filamin A in cancers resulting from exposure to As3+ or other environmental carcinogens." (PMID 25944616, 2015). "Filamin A, for example, has been reported as a target for DNA damage-based cancer therapy." (PMID 24858105, 2014). "Although FLNA mutations can be the cause of human genetic disease, increased cancer incidence has not been observed in these patients." (PMID 23388158, 2013). "A Gene profiling approach was also employed to assess filamin-A expression in human cancer." (PMID 23388158, 2013). "However, the specific consequence of filamin-A inhibition in metastasis and DNA damage sensitivity is likely dependent on the cancer stages and types of DNA damage agents." (PMID 23388158, 2013). "A further implication of these findings is that expression level of filamin-A in cancer cells may be exploited as a biomarker to predict the effectiveness of different types of therapeutic DNA damage agents to the cancer subtype." (PMID 23388158, 2013). "The alteration of FLNa expression may contribute to cancer development and progression, and previous studies have identified FLNa overexpression in a number of malignancies." (PMID 24137390, 2013). "The role of filamin-A in DNA damage response presents an intriguing possibility that targeting filamin-A may be useful for cancer therapy." (PMID 23388158, 2013). "In this review, we discuss the role of filamin-A in human diseases, with an emphasis on cancer." (PMID 23388158, 2013). "It is known than filamin-A interacts with many proteins related to cancer metastasis." (PMID 23388158, 2013). "Due to its functions in the control of cell mobility, cell-ECM interactions, cell signaling, and DNA damage response, it is conceivable that filamin-A may be developed as a biomarker for cancer diagnosis and outcome prediction." (PMID 23388158, 2013).